EGFR (epidermal growth factor receptor)
Diseases named in the same sentence as EGFR in open-access papers (continued):
Sharing a sentence is not in itself a finding about the gene and the disease.
lymph node metastasis (continued). "SPA subtype and the presence of solid pattern are associated with numerous poor prognostic factors, including higher mitotic count, high risk of occult lymph node metastases, thyroid transcription factor-1 (TTF-1) negativity, and less frequent epidermal growth factor receptor (EGFR) mutations." (PMID 38450191, 2024). "The expression of USP5 was not related to gender, age, lymph node metastasis, pathological grade, the EGFR mutation and ALK translocation but was related to tumor size, and the difference was statistically significant." (PMID 36611139, 2023). "Therefore, EGFR-mutant patients with stage II–IIIA disease, especially those with lymph node metastases, can benefit from adjuvant EGFR-TKI treatment after resection." (PMID 36782320, 2023). "However, EGFR+/CD3+ expression was most frequently observed in younger males (p=0.01) and associated with less lymph node metastasis (p=0.046) compared to EGFR+/CD3- patients." (PMID 35957892, 2022). "In addition, among male subjects having mutant EGFR, patients carrying allele T in TIMP-3 rs9862 exhibited a higher risk of displaying an advanced stage and positive lymph node metastasis." (PMID 35813301, 2022). "Lymph node metastasis was detected in 5 patients with the same EGFR mutation, although this was not significant (p = 0.053)." (PMID 35740676, 2022). "In the non-squamous NSCLC, the role of EGFR mutations on of lymph node metastasis have not been fully investigated and more works are needed to elucidate the molecular mechanisms." (PMID 36401689, 2022). "We also found a significant association between patients with lymph node metastasis and overexpression of BMP7 (47.4%, P=0.005), CALD1 (42.1%, P=0.020), CDH1 (52.6%, P=0.001), COL3A1 (42.1%, P=0.020), EGFR (47.4%, P=0.005), ERBB3 (57.9%, P=0.000), PLEK2 (47.4%, P=0.024), and TCF4 (52.6%, P=0.001)." (PMID 34527572, 2021). "The LCOs were generated from the biopsy of the progression disease (PD) lymph node metastasis where the EGFR L858R mutation was still present and the EGFR T790M mutation was absent." (PMID 33972544, 2021). "The results also indicated that the low expression of AMPK was positively correlated with lymph node metastasis (P = .016, χ2 test) and tumour T stage (P = .026, χ2 test), but not with epidermal growth factor receptor (EGFR) mutation rate (P > .05, χ2 test)." (PMID 32519437, 2020). "The patients without lymph node metastasis (P = 0.012) in early stage disease (P < 0.001) exhibited a higher EGFR mutation rate." (PMID 32729257, 2020). "Among ADC patients, PD-L1 positivity was significantly more frequent in male patients (p=0.027), smokers (p=0.027), stage II/III/IV patients (p=0.008), patients with lymph node metastasis (p < 0.0001), carriers of wild-type EGFR (p=0.004), and at higher SUVmax values (p < 0.0001)." (PMID 32765198, 2020). "Patients without lymph node metastasis (P = 0.012), or early stage disease (P < 0.001) exhibited a higher EGFR mutation rate." (PMID 32729257, 2020). "Furthermore, serum LAPTM4B levels were positively correlated with smoking, advanced clinical stages, lymph node metastasis, ALK rearrangements and EGFR mutations." (PMID 30940109, 2019). "EGFR exhibits a positive correlation with lymph node metastasis." (PMID 30237984, 2018). "EGFR positivity was associated with lymph node metastasis and UICC stage of the patients, which may result from the well-known role of EGFR in proliferation, invasiveness and migration of tumor cells." (PMID 28859123, 2017). "EGFR gene amplification was related to lymph node metastasis (χ2 trend test: p = 0.018)." (PMID 28854970, 2017). "Patients with EGFR mutations without lymph node metastases also had higher nuclear expression of P-s207 LysRS (50%) as compared to patients with lymph node metastases (27.8%) (p = 0.021)." (PMID 29029422, 2017).
lymph node metastasis (continued). "We could predict two-thirds of the EGFR gene copy number alterations for the lymph node metastasis group or the recurrence tumor group from analysis of the primary tumor." (PMID 28854970, 2017). "The patient’s EGFR CA repeat genotype was found not to be associated with tumor stage, tumor differentiation, lymph node metastasis or tumor aggressiveness factors, including skin, bone and perineural invasion." (PMID 28694429, 2017). "High EGFR expression was found to be significantly related with tumor differentiation (OR=1.96, 95%CI: 1.14-3.34, Z=2.43, P=0.015), lymph node metastasis (OR=2.20, 95% CI: 1.63-2.96, Z=5.17, P=0.001), and tumor stage (OR=2.13, 95% CI: 1.35-3.36, Z=3.25, P=0.001)." (PMID 28199988, 2017). "Importantly, our analyses of the mitochondrial localization of Tid1-S and EGFR in clinical specimens from NSCLC patients reveal a very good correlation between high levels of mitochondrial Tid1-S/EGFR and lymph node metastasis and poor overall survival." (PMID 28714950, 2017). "Differences in proportions of the other elements were not consistent in comparisons between EGFR-mutated LADCs with lymph node metastasis and the other groups." (PMID 27861549, 2016). "EGFR amplification was associated with lymph node metastasis (P = 0.028), but not correlated with DFS and OS until 20 months." (PMID 25953424, 2015). "Further studies are necessary to examine whether tumors with Ex19, which is indicative of malignancy that is an intermediate grade (between Wt and Ex21), present with lymph node metastasis at the highest frequency of the 3 EGFR statuses." (PMID 26496308, 2015). "EGFR overexpression was found to correlate with the presence of lymph node metastasis (P=0.011)." (PMID 24944678, 2014). "However, other previous studies have also demonstrated that EGFR amplification or overexpression significantly correlates with lymph node metastasis." (PMID 24944678, 2014). "However, EGFR over-expression was correlated with lymph node metastasis, the probability of lymph node metastasis was significantly greater in patients with EGFR over-expression than in EGFR negative group (P = 0.006)." (PMID 21385353, 2011). "The overexpressions of VEGF-C and EGFR genes are closely related to lymph node metastasis." (PMID 21159248, 2010). "However, statistically significant differences were observed in tumor T stage, lymph node metastasis, tumor necrosis, EGFR, and tumor markers, and in general, the higher expression of AGRN was more pronounced in patients with later stage and lymph node metastasis." (PMID 39691475, 2024). "Additionally, there are no obvious differences of positive ratio among gender, age, clinical stage, lymph node metastasis, distant metastasis, ALK mutation status, EGFR mutation status and PDL1 expression (P>0.05) except diameter between high UBQNL1 expression and low UBQNL1 expression." (PMID 38431566, 2024). "The predictive model with the univariate Cox regression analysis, clinical covariates of pathologic stage, tumor size, and lymph node metastasis had some predictive value; however, sex, age, race, EGFR mutation, gross pathology, and distant metastasis did not correlate with OS." (PMID 34036102, 2021). "SGLT1 expression was associated with gender and age, but not smoking behavior, EGFR mutation status, tumor size, lymph node metastasis, pathological stage, or immediate response to EGFR TKIs, with higher SGLT1 expression, detected in NSCLC tumors of males aged over 55 years." (PMID 34155348, 2021). "Due to the mutations of KRAS and EGFR in NSCLC are mutually exclusive, we divided our LUAD patients into WT and MT EGFR subgroups and found that the T allele of rs8193036 was only correlated with an advanced stage and lymph node metastasis in LUAD patients harboring the WT EGFR." (PMID 33802737, 2021).
lymph node metastasis (continued). "However, our survival analysis results identified only N stage among the clinicopathological factors as a risk factor for predicting PFS in patients receiving EGFR-TKI treatment, while lymph node metastasis is a well-established prognostic feature for predicting the prognosis of NSCLC." (PMID 34796106, 2021). "It is well-established that EGFR overexpression and abnormal activation is a dominant oncogenic signal for the development of many human malignancies including NSCLC, which is associated with reduced survival, frequent lymph node metastasis and poor chemo-radiation sensitivity." (PMID 30918250, 2019). "It was also observed that patients with an EGFR mutation in exon 19 or 21 and no lymph node metastasis had longer DFS when P-s207 LysRS was present in the nucleus compared to patients with absent nuclear P-s207 LysRS, 67.5 months vs. 52.4 months respectively (p = 0.046)." (PMID 29029422, 2017). "Surgically resected tumors (EGFR-mutated LADCs with and without lymph node metastasis and EGFR wild-type LADCs with and without lymph node metastasis) and biopsy samples from inoperably advanced tumors (EGFR-mutated LADCs and EGFR wild-type LADCs) were examined." (PMID 27861549, 2016). "Similarly, despite extensive study, ambiguity surrounds the role of EGFR in lymph node metastases." (PMID 24401183, 2013). "In EHCC, EGFR expression was significantly associated with macroscopic type (0% in the polypoid type, 24.0% in the non-polypoid type; P=0.0120), lymph node metastasis (P=0.0006), UICC Stage (P=0.0424), lymphatic vessels invasion (P=0.0371), and perineural invasion (P=0.0459)." (PMID 18087285, 2008). "In particular, for patients undergoing treatment with EGFR TKIs, there is evidence of poor PFS and cancer-specific survival, as well as a correlation with lymph node metastases." (PMID 41153394, 2025). "Other genes showing high fold change were FGF19 (highest 14.4 in a lymph node metastasis sample), CCND1 (highest 14.3 in a lymph node metastasis samples), and EGFR (highest 11,0 in a tumor sample)." (PMID 39324009, 2024). "LC_08PE patient was diagnosed as a tumor with MPE and lymph node metastasis and was resistant to the ALK-targeted drug alectinib, despite being positive for EGFR exon 19 deletion and ALK rearrangement." (PMID 37993887, 2023). "Lymph node metastasis, chemotherapy, and EGFR status significantly differed depending on ALKBH5 expression, whereas tumor status, lymph node metastasis, pathological stage, chemotherapy, and EGFR status significantly differed depending on FTO expression." (PMID 35318440, 2022). "In the case of lymph node metastasis, the levels of MSI1 mRNA expression were higher than the EGFR expression in tumors with metastatic lymph nodes (1.02 ± 0.46 vs. 0.61 ± 0.47, fold changes)." (PMID 30202417, 2018). "Tumor specimens after acquisition of resistance to EGFR-TKI treatment were derived from the primary lung lesion in 7 patients, pleural effusion in 8, lymph node metastasis in 2, and pericardial effusion in one." (PMID 26334838, 2015).
lymph node metastasis (continued). "In the univariate survival analysis, lymph node metastasis, advanced TNM stage, positive resection margins, poor tumor differentiation, CXCR4 expression and EGFR/CXCR4 coexpression were significant prognostic factors for poor DFS and OS." (PMID 25679210, 2015). "In our search, 24.4% (10/41) and 34.1% (14/41) of patients with lymph node metastases harbored ERBB2 and EGFR gene amplification, respectively." (PMID 21689422, 2011). "The EGFR is commonly expressed in NSCLC, its expression in the primary tumor and the corresponding lymph node metastasis is discordant in about 10% of the patients." (PMID 20096104, 2010). "Univariate analysis revealed that Beclin 1 level, EGFR and ALK mutations were associated with lymph node metastasis, TNM stage, tumor differentiation and prognosis, but not with gender, age and smoking status." (PMID 36401689, 2022). "Univariate analysis showed that Beclin 1 expression and EGFR and ALK mutations were associated with lymph node metastasis, TNM stage, tumor differentiation and prognosis, but not with gender, age and smoking status (P < 0.05)." (PMID 36401689, 2022). "Among MPLA patients, nonsmoking women with less lymph node metastasis and patients with lesions presenting GGO or mixed GGO and air bronchograms on CT were more likely to exhibit EGFR mutations." (PMID 32690092, 2020). "In conclusion, among patients with MPLAs, nonsmoking women with less lymph node metastasis and patients who present with GGO and air bronchograms on CT are more susceptible to EGFR mutations." (PMID 32690092, 2020). "Positivity for EGFR and double positivity for EGFR and HER2 (EGFR+/HER2+/c-Met+ and EGFR+/HER2+/c-Met-) were significantly correlated with lymph node metastasis (P = 0.010 for single and P = 0.013 for double) and UICC stage (P = 0.021 for single and P = 0.007 for double)." (PMID 28859123, 2017). "Regarding positivity of multiple RTKs, double positivity for EGFR and HER2 (EGFR+/HER2+/c-Met+ and EGFR+/HER2+/c-Met-) was significantly correlated with tumor size in addition to lymph node metastasis and UICC stage, which were also correlated with single EGFR positivity." (PMID 28859123, 2017). "Tumors with high levels of tumor invasion, lymph node metastasis, bone invasion and perineural invasion had a significantly higher frequency of EGFR gene amplification than tumors without those characteristics." (PMID 28854970, 2017). "Conversion between primary tumour and lymph node metastasis had no prognostic impact for EGFR or HER3 (p = 0.998 and 0.375, respectively, data not shown)." (PMID 26844548, 2016). "In ESCC, EGFR overexpression was significantly correlated with clinical stage and lymph node metastasis (p<0.05), but not with other independent variables." (PMID 27013591, 2016). "To investigate the clinical outcome due to the over-expression of Flot-2 and EGFR in cancer tissues, we next investigated clinicopathological features of NSCLC including age, gender, clinical stages, lymph node metastasis (LNM) status, and pathological differentiation in univariate chi-square test." (PMID 26161893, 2015).
lymph node metastasis (continued). "EGFR reactivity was not correlated with gender, age, differentiation, lymph node metastasis or distant metastasis." (PMID 22139134, 2012). "The expressions of VEGF-C mRNA and EGFR mRNA were much higher in patients with lymph node metastasis than those without lymph node metastasis (P < 0.05)." (PMID 21159248, 2010). "The pooled data showed that patients with lymph node metastasis exhibited significantly higher levels of EGFR expression than were observed in patients without metastasis, with a combined OR of 1.72 (95% CI: 1.23–2.40) and without heterogeneity (I2 = 0.00%, Ph = 0.862)." (PMID 27438047, 2016). "Furthermore, among patients without EGFR mutation, those who have at least one polymorphic A allele of IGF1R rs7166348 have an increased incidence of lymph node metastasis when compared with those patients homozygous for GG (OR, 2.75; 95% CI, 1.20–2.31)." (PMID 27213344, 2016). "EGFR gene amplification was not identified to differ significantly in patients with regard to gender, age, tumor location, tumor-node-metastasis stage, tumor size, lymph node metastases or involvement of the pleura." (PMID 25013472, 2014). "Furthermore, we found that the increased expression of EGFR protein was more frequent in lymph node metastasis of NSCLC compared to non-metastatic NSCLCs (27 vs. 14 or 45 % vs. 23.3 %; P = 0.009)." (PMID 22537942, 2012). "Remarkably, the exosomal levels of these proteins, including the EGFR, correlated with clinicopathological parameters, being higher in patients with stage III/IV disease and lymph node metastases versus those with stage I/II disease and without lymph node metastases." (PMID 36817764, 2023). "Due to the emergence of EGFR inhibitor resistance, to find more effective and new tumor regulation sites, we specifically selected specimens from OSCC patients with or without lymph node metastasis under the same T2 stage classification in this study and compared their mRNA expression profiles." (PMID 36899380, 2023). "The EGFR status did not correlate with disease-specific survival (DSS, p = 0.551), tumor localization (p = 0.369), tumor size (p = 0.690), lymph-node metastasis (p = 0.525), distant metastasis (p = 0.522), stage (p = 0.182), smoking (p = 0.866) or alcohol consumption (p = 0.707)." (PMID 36769112, 2023).